ECT2 (epithelial cell transforming 2)
Diseases named in the same sentence as ECT2 in open-access papers (continued):
Sharing a sentence is not in itself a finding about the gene and the disease.
tumor (continued). "The group was headed by MCM2, ECT2, and RFC4, which are associated with DNA replication, DNA repair or positive regulation of signal transduction, indicating that these genes are essential for tumor growth." (PMID 24879114, 2014). "ECT2 is a biomarker that can be used for diagnosis and prognostic prediction in HCC, and its overexpression could promote lactic acid production through the ECT2/PLK1/PTEN pathway, enhance tumor-associated macrophage infiltration, and suppress immune cell function." (PMID 37957902, 2024). "Moreover, the higher ECT2 expression in late stage compared to early stage patients with high CEA expression suggested that ECT2 might predict tumor stage and clinical outcome in colorectal patients." (PMID 28362321, 2017). "E2F1, which is highly expressed in tumor cells, may also contribute to Ect2 up-regulation." (PMID 27074761, 2016). "Recent studies have shown that ECT2 can abnormally activate RhoA, and then the activated RhoA binds to ROCK, participating in the abnormal proliferation and migration of various tumor cells by mediating various cascade reactions." (PMID 40655948, 2025). "Among these, key genes including TMEM106C, ECT2, PSMD2, STIL, and TTK showed significant upregulation in tumor tissues, and their high expression may be closely associated with abnormal activation of tumor stem cells, cell cycle regulation, and enhanced self-renewal capacity." (PMID 40766320, 2025). "Comprehensive differential expression analysis between normal and tumor tissues revealed complex regulatory patterns of stem cell marker genes, with key genes such as TMEM106C, ECT2, PSMD2, STIL, and TTK showing significant upregulation in tumor tissues." (PMID 40766320, 2025). "Moving to the NKT cells, the opposite correlation was demonstrated in 80% of the analyzed tumors, with the presence of only one tumor, LIHC, that showed a positive correlation between ECT2 and NKT cell levels." (PMID 37106813, 2023). "CDK1, ECT2, EZH2, GJB2, GPR37, GPX2, and GPX8 mRNA expression was up-regulated in the tumor group (p < 0.001), whereas GPX3, HYAL1, and TLR4 mRNA expression was down-regulated in the tumor group (p < 0.001) compared with those in the normal group." (PMID 37689745, 2023). "The expression of CDK1, ECT2, GJB2, GPR37, GPX2, and GPX8 gene was up-regulated in the tumor group (p < 0.001), whereas the expression of TLR4 was down-regulated in the tumor group (p < 0.001) when compared with those in the normal group." (PMID 37689745, 2023). "Studies have shown that high ECT2 expression predicts the progression of NSCLC and the poor prognosis, and is related to the proliferation, survival, and invasion of tumor cells." (PMID 36311939, 2022). "The clinical correlation of key genes was analyzed, and the results showed that the expression of ECT2 and COL17A1 was significantly correlated with tumor grade (P < 0.05)." (PMID 35722628, 2022). "Among these genes, the mRNA levels of ECT2, HNRNPK, P4HA1, and TUBA4A were significantly upregulated in the tumor tissues, when compared to those in normal tissues." (PMID 35284334, 2021). "Another meta-analysis approach based on PDAC datasets allowed the identification of a 5 genes classifier signature (TMPRSS4, AHNAK2, POSTN, ECT2, SERPINB5) with 95% sensitivity and 89% specificity in discriminating PDAC from non-tumor samples." (PMID 30236127, 2018). "Among the top dysregulated genes when comparing control and tumor free tissue were those involved in apoptosis (CIDEC, MUC1, ZBTB16, PRNP, ECT2), immune response (IFI27) and differentiation (KRT36)." (PMID 28038473, 2017). "These links between ECT2 and RAS signalling make this an attractive and novel target worthy of further investigation for pro-senescence therapy of KRAS mutant tumours." (PMID 28806777, 2017).
tumor (continued). "Even for the therapy-naïve study cohort, differential gene expression was a significant prognosticator within tumor sets defined by their WHO grades (WHO°I: AURKB, COX10, ECT2, UBE2C; WHO°II: LEPR, MN1; WHO°III: PTTG1, UBE2C)." (PMID 26894859, 2016). "Five of the GEFs described to promote GB cell motility, including Ect2, Vav3, Trio, SGEF, and SWAP-70, are overexpressed in GB versus non-neoplastic brain, and Dock180 expression is higher in the tumor rim than in the tumor core." (PMID 24109588, 2013). "However, in tumor cells, the NLS structure of ECT2 is missing, resulting in its mislocalization into the cytoplasm, the disappearance of its auto-inhibitory effect, and then the activation of Rho family GTPase to drive transformation." (PMID 40655948, 2025). "While the oncogenic roles of ECT2 have obtained a large focus in the last few years, there is still a lack of comprehensive studies that can analyze the roles of ECT2 in tumor progression from different aspects." (PMID 37106813, 2023). "Additionally, the expressions of ECT2, FGD6, MMP14, and SLC2A1 were related to the staging of the tumor." (PMID 37604837, 2023). "It is important to mention that not a single tumor showed a negative correlation between ECT2 and these cells with the immunosuppressive roles." (PMID 37106813, 2023). "Besides, we also discovered that the average expressions of two genes, ECT2 and RNFT2, increased concordantly with the tumor stage progression." (PMID 36400805, 2022). "Blocking ECT2 and its downstream signaling pathway would be meaningful to transform tumor cells from hyperactive proliferation towards non-division state." (PMID 36572949, 2022). "ECT2 also plays a tumor-promoting role in a number of other cancers, such as non-small cell lung cancer and breast cancer." (PMID 33558466, 2021). "According to the CPTAC data, the protein expression of PKMYT1, ETF1, ECT2, BUB1B, and RECQL4 in tumor tissues was significantly increased, while the expression of TFRC was significantly reduced, and the expression of COCH and TUBB2B did not change significantly (PITX1 and CDC6 were not included)." (PMID 33869220, 2021). "Of these seven, six genes—ECT2, NCEH1, TNFSF10, FNDC3B, GHSR, and SEMA6D—have either been observed at elevated expressions in tumor cells or have been documented acting as oncogenes for specific cancers in humans (genes that can transform cells into tumor cells)." (PMID 33767816, 2021). "Overall, abundant studies have confirmed a role for ECT2 in promoting tumor malignancy, but no further evidence has been presented to support a suppressive role of ECT2 in tumor malignancy." (PMID 28362321, 2017). "A 5-gene PDAC classifier (TMPRSS4, AHNAK2, POSTN, ECT2, SERPINB5) achieved on average 95% sensitivity and 89% specificity in discriminating PDAC from non-tumor samples in four training sets and similar performance (sensitivity = 94%, specificity = 89.6%) in five independent validation datasets." (PMID 26993610, 2016). "We assessed ANLN and ECT2 expression differences in tumor versus non-malignant tissue." (PMID 38785827, 2024). "The mechanisms responsible for the high expression of ECT2 in various tumor tissues are unknown, and no study has investigated the TFs that regulate ECT2." (PMID 38467631, 2024). "ECT2 was found to be highly expressed in tumor tissues versus normal ones." (PMID 37106813, 2023). "Moreover, the analysis of independent prognostic and clinical correlations demonstrated that ECT2 and COL17A1 could not only be independent prognostic factors of PC but also positively correlated with tumor grade." (PMID 35722628, 2022). "We found that tumor growth retardation resulted from ECT2 depletion could be largely reverted by ECT2/wt, while ECT2/GEFmt also showed a detectable compensation effect, albeit not as effective as ECT2/wt." (PMID 32929379, 2020). "We validated ANLN and ECT2 mRNA expression in tissue, utilizing the TCGA PRAD and an AA non-malignant/tumor-matched clinical cohort." (PMID 38785827, 2024).
tumor (continued). "On the other hand, four tumors (ACC, LGG, SRAC, and TGCT) demonstrated nonsignificant differences and only one tumor, LAML, experienced a significantly higher ECT2 expression in normal tissues versus cancerous ones." (PMID 37106813, 2023). "In our AA prostate contralateral benign-tumor-matched cohort (n = 73), ANLN was shown to be nominally overexpressed in tumors compared to non-malignant (p = 0.06), while ECT2 was significantly overexpressed in tumor compared to non-malignant matched tissue (p < 0.00001)." (PMID 38785827, 2024). "In the HPA data, compared with normal tissues, the expression of PKMYT1, ETF1, RECQL4, TUBB2B, and CDC6 in tumor tissues was remarkably upregulated, while the expression of TFRC and PITX1 was significantly downregulated (,ECT2, BUBB1B, and COCH were not included)." (PMID 33869220, 2021). "Here, knockdown of ECT2 induced a more complete senescence response in HCT116 cells with KRASG13D, but not in MCF10a non-neoplastic breast epithelial cells irrespective of KRASG13D, suggesting a possible tumour-specific effect." (PMID 28806777, 2017).
cancer (61 papers, 2009 to 2026). A tumor composed of atypical neoplastic, often pleomorphic cells that invade other tissues. "The most common GEFs implicated in cancer are T-cell lymphoma invasion and metastasis 1 (Tiam1), Trio, Vav1/2/3, Ect2, Phosphatidylinositol 3,4,5-trisphosphate (PIP3)-dependent Rac exchanger 1 (P-Rex1), and Dock1." (PMID 32322580, 2020). "In support our data, a recent study reported that several cancer types are associated with increased expression and activity of the ECT2 RhoGEF and decreased expression and activity of the DLC1 RhoGAP, leading to increased RhoA activity." (PMID 30278072, 2018). "Inactivation of ECT2 was shown to be sufficient to prevent cell death induced by ionizing radiation underlying its potential important role in resistance to cancer therapy resistance." (PMID 26427052, 2015). "Epithelial cell transforming sequence 2 (ECT2) is a guanine nucleotide exchange factor for Rho family GTPase, which has been implicated in the malignant phenotype of human cancers." (PMID 21124766, 2010). "Overexpression of ECT2 has been reported to be associated with cancer, and the DNA methylation status in promoter regions plays a key role in regulating its expression during cancer progression." (PMID 39628446, 2024). "ECT2 has been thought to be associated with a variety of cancers." (PMID 33062405, 2020). "Ect2 has been shown to be overexpressed in multiple cancers and associated with poor survival." (PMID 32322580, 2020). "Integration of the recurrent regions identified by WACE and the gene regulatory network analysis uncovered not only many well-known oncogenes like BIRC5and E2F1, but also a number of novel cancer susceptibility genes such as ECT2, TPX2 and TACC3, which are involved in cell cycle and ECM regulation." (PMID 21806811, 2011). "Therefore, if the structural changes in the BRCT domain and then cause ECT2 function mutations, it may lead to tumors or cancer." (PMID 40655948, 2025). "We, thus, tested if the disruption of both anillin and Ect2 functions is detrimental to successful cancer cell extravasation." (PMID 40571734, 2025). "Epithelial Cell Transformation Factor 2 (ECT2) is highly expressed in a variety of cancers, including gynecological tumors." (PMID 40655948, 2025). "After injecting cancer cells with high ECT2 expression into mice, the volume and weight of tumors in mice increased significantly compared to the control group." (PMID 40655948, 2025). "ECT2 is overexpressed in various cancers such as non-small lung cell carcinoma, glioblastoma, and prostate cancer." (PMID 40655948, 2025). "In terms of treatment, previous studies have shown that ECT2 in cancer cells overcomes endogenous DNA damage by promoting double-strand break (DSB) repair to maintain their survival and reduce the effect of radiotherapy or chemotherapy." (PMID 40655948, 2025). "As a guanine prenucleotide change factor of Rho GTPase, high ECT2 is a factor for poor prognosis in cancer patients." (PMID 40655948, 2025). "To study the roles of anillin and Ect2 in cancer cell invasion in vivo, we employed an ex ovo chick embryo cancer xenograft model." (PMID 38260442, 2024). "We thus tested if disruption of both anillin and Ect2 function is detrimental for successful cancer cell extravasation." (PMID 38260442, 2024). "Many evidences indicate that the irregular activity of ECT2 is involved in different cancer types and the reduction of ECT2 suppresses tumorigenesis." (PMID 39552710, 2024). "Comparison of regulatory variants across populations revealed regulatory effects in GM only for genes implicated in cancer, including ST7, SET and ECT2." (PMID 37543566, 2023).
cancer (continued). "Epithelial cell transforming 2 (ECT2) is a potential oncogene and a number of recent studies have correlated it with the progression of several human cancers." (PMID 37106813, 2023). "Consistent with that, the current study revealed the hypomethylation status of ECT2 (as both promoter and CpG-aggregated hypomethylation) in a large set of human cancers." (PMID 37106813, 2023). "The KEGG results showed that the cell cycle, pathways in cancer, and proteasome were greatly enriched in the high-expression group of ECT2 and COL17A1 (P < 0.05)." (PMID 35722628, 2022). "It has been detected that ECT2 was overexpressed in various cancers, including non-small lung cell cancer, glioblastomas, and prostate cancer." (PMID 36572949, 2022). "Even though the oncogenic role of splicing variant of ECT2 without nuclear localization signal was verified in mice model, human cancer cells express full-length ECT2." (PMID 36572949, 2022). "Amongst the Cdc42 GEFs, many Dbl family members are altered in cancers, for example Ect2, Tiam-1, Trio, P-Rex1–2 and Vav1–3." (PMID 34196668, 2021). "In some cancers, Ect2 overexpression is driven by amplification of the ECT2 gene as part of the chromosome 3q26 amplicon, a common chromosomal mutation in human cancers." (PMID 33546351, 2021). "We also used the TIMER database to analyze the expression levels of ECT2 in pan-cancer, which were consistent with those found by using Oncomine, with ECT2 expression being significantly higher in most cancers compared to the control group." (PMID 33558466, 2021). "In conclusion, we identified ECT2 as a cancer biomarker that can be used for diagnosis and prognostic prediction in HCC." (PMID 33558466, 2021). "Inhibitors targeting Ect2 have yet to be identified, but it is imperative to develop specific inhibitors to block the activation of Rho GTPases by Ect2 in cancer cells." (PMID 32322580, 2020). "Gene set enrichment analysis revealed that high ECT2 expression was enriched for hallmarks of malignant tumors." (PMID 33062405, 2020). "This study demonstrates the importance of the evolutionarily conserved interaction between Prickle1 and Ect2, which appears to be reactivated during tumorigenesis to promote cancer cell dissemination and metastasis." (PMID 30971775, 2019). "That is because normally the phosphorylation of ECT2 will activate Rho family GTPase to promote cancer progression." (PMID 29706628, 2018). "Briefly, paclitaxel favors the production of ECT2-S, the short splicing isoforms of ECT2, thereby inhibiting cancer cell proliferation." (PMID 29706628, 2018). "Further confirmation of ECT2 as a possible marker for CTC detection was obtained by estimating the mRNA expression of ECT2 by cells from peripheral blood from colorectal patients and non-cancer donors." (PMID 28362321, 2017). "In LUAD, ECT2 co-expressed genes were additionally enriched in some cancer-related pathways, such as Pyrimidine metabolism, Ribosome biogenesis in eukaryotes, RNA transport and Base excision repair." (PMID 29088286, 2017). "Prognostic significance of elevated ECT2 mRNA expression has been evaluated and positively correlated with protein expression in a range of cancer types." (PMID 28806777, 2017). "Hirata reported to identify ECT2 as a candidate prognostic biomarker and regulate cancer cell growth." (PMID 29108269, 2017). "ECT2 is upregulated in several human cancers and functions as an oncogene." (PMID 38467631, 2024). "We showed that ECT2 could be considered as a prognostic and immunological biomarker in a list of human cancers through the investigation of several databases." (PMID 37106813, 2023). "However, accumulated ECT2 in the cytoplasm of cancer cell leads to hyperactive Rho GTPases, which promotes epithelial-to-mesenchymal transition, loss of cell polarization, formation of invadopodia/ lamellipodia/ filopodia, and tail retraction." (PMID 36572949, 2022). "In cancer tissues, we found abnormal ECT2 staining in cytoplasm." (PMID 36572949, 2022).